DIS3 (DIS3 exosome endoribonuclease and 3'-5' exoribonuclease)
Diseases named in the same sentence as DIS3 in open-access papers (continued):
Sharing a sentence is not in itself a finding about the gene and the disease.
tumor (18 papers, 2012 to 2026). "Critically, patients with DIS3 mutations exhibit significantly more 14q32 translocations than control patients, suggesting a role for DIS3 as a tumor suppressor, particularly for preventing aberrant pathological DNA recombination." (PMID 41286079, 2026). "Although recent studies have revealed the molecular functions of FAM46C and its tumor-suppressive roles in MM, the biological significance of DIS3 mutations in MM remains poorly understood." (PMID 36835493, 2023). "Reduction-of-function mutations in DIS3 seem to arise early in tumorigenesis, implicating DIS3 as a potential tumor-suppressor gene." (PMID 30724665, 2019). "DIS3 is mutated in both primary tumour and relapse samples at a VAF between 37% and 47%, suggesting a heterozygous event in these cases." (PMID 26193331, 2015). "Patients carrying DIS3 mutations in minor subclones of their tumours also showed a significantly worse response to therapy compared to patients with DIS3 mutations in the major subclone." (PMID 26193331, 2015). "Altogether, these data strongly suggest that DIS3 deficiency causally leads to increased genomic instability and that DIS3 may act as a tumor suppressor gene in this cancer." (PMID 41286079, 2026). "Low allele frequencies (< 0.3) suggested that Dis3 and Rara mutations were subclonal, whereas a single copy of Ctnnb1 1004A>C (K335T substitution) with an allele frequency of 0.48 was likely to be clonal and thus possibly involved in tumor initiation." (PMID 35510955, 2022). "The observations that DIS3 causes cell cycle arrest in many mutants may at first appear illogical in relation to its role in MM as a tumour suppressor gene." (PMID 26193331, 2015). "Recent mechanistic studies further support the notion that DIS3 is a tumor suppressor, which we discuss later in this review." (PMID 36835493, 2023). "Although its role in the pathogenesis of the disease remains to be further elucidated, DIS3 is considered a potential tumor suppressor in MM." (PMID 26305418, 2015). "In this study, we provide evidences that DIS3 inactivation stimulates oncogenic signaling pathways through a down-regulation of the tumor suppressor miRNA family let-7." (PMID 25925570, 2015). "Our findings point to a crucial role for the ribonuclease DIS3 in promoting the maturation of the let-7 miRNA tumor suppressor family, through a DIS3-mediated control of the pluripotency factor LIN28B." (PMID 25925570, 2015). "Concerning DIS3, although its role in the pathogenesis of the disease remains to be elucidated, this gene was characterized as potential tumor suppressor in MM." (PMID 26046463, 2015). "Two independent gene expression profiling studies of colorectal cell lines and human tissues identified overexpression of DIS3 as high as 38-fold in primary and metastatic tumours relative to normal colonic mucosa." (PMID 26193331, 2015). "Using transgenic flies, we show that Dis3 knock down (Dis3KD) retards growth, induces melanotic tumor formation, and ultimately results in 2nd instar larval lethality." (PMID 22853036, 2012). "These events may include mutations in key genes that when estimated as % of the tumor population emerge as subclonal events in different MM patients: KRAS (20–72%), NRAS (32–96%), BRAF (36–92%) or DIS3 genes (29–81%)." (PMID 25929340, 2015). "Furthermore, very recently we demonstrated that DIS3 facilitates the maturation of the tumor suppressor let-7 miRNAs by reducing in the cytoplasm the RNA stability of the pluripotency factor LIN28B, an inhibitor of let-7 processing." (PMID 26305418, 2015). "However, whether DIS3 is an oncogene or tumour-suppressor gene remains to be proven by functional investigations." (PMID 26193331, 2015).
tumor (continued). "Through interaction with DIS3 as a possible tumor suppressor, GTPBP1 can progress tumor progression in ATLL." (PMID 35041720, 2022). "Among the genes significantly co-activated in G3 basal-like tumor samples, we identified 3 reproducible and concordantly up-regulated SAGPs (ABI1/PDSS1, DIS3/BORA and WDR77/ATP5F1)." (PMID 26517092, 2015). "As a result, we examined DIS3 expression in KIRC tissues and non-tumor tissues and observed that DIS3 expression in KIRC tissues was slightly lower than in non-tumor tissues." (PMID 34512342, 2021). "All together, these data suggest that DIS3 does not pervasively regulate miRNAs, but rather impacts only on a very limited set of miRNAs, specifically affecting the miRNA family of tumor suppressor let-7." (PMID 25925570, 2015). "Here we found that DIS3 regulates the levels of the tumor suppressor let-7 miRNAs without affecting other miRNA families." (PMID 25925570, 2015).
cancer (17 papers, 2012 to 2026). A tumor composed of atypical neoplastic, often pleomorphic cells that invade other tissues. "With respect to human diseases, DIS3 has been shown to be associated with various types of cancer, including colorectal cancer, melanoma, and three types of hematological malignancies." (PMID 38689093, 2024). "Although the mechanistic consequences of DIS3 mutations are largely unclear, a recent report has described that cancer-associated DIS3 mutations cause mitotic defects and genome instability without increased DNA damage and RNA processing defects in yeast." (PMID 34948199, 2021). "Here we report that a cancer-associated DIS3 allele, dis3E729K, provides evidence for DIS3 functioning in mitotic fidelity in yeast." (PMID 30724665, 2019). "Recently, aberrant expression of DIS3 has been found to be implicated in a range of different cancers." (PMID 26193331, 2015). "Curiously, in cancer, DIS3 mutations have been found in MM and, at a lower percentage, in AML, while mutations in this gene have not been reported in the sequencing efforts ongoing in epithelial cancers, with hundreds of patient genomes screened as of today." (PMID 25925570, 2015). "Indeed, variants in DIS3 and exosome components have been implicated in other diseases such as cancer." (PMID 39400047, 2025). "DIS3, encoding the exosome endoribonuclease and 3′-5′ exoribonuclease, is a highly conserved gene required for mitotic progression and is involved in several cancers." (PMID 26517092, 2015). "In addition, the loss of cell division and increased cell size phenocopy, in part, transformed cells in human cancer, which may provide a possible mechanism of DIS3 mutations causing genomic instability, DNA repair defects, and genome rearrangement in human disease." (PMID 36724075, 2023). "Seven genes (BORA, DIS3, POLR2C, FAM175A, EME1, RNF139 and SHMT1) are considered potential biomarkers and/or potential targets for radiotherapy and chemotherapy, as well as cancer susceptibility, cancer progression and metastasis-related genes." (PMID 26517092, 2015). "One possible explanation for the selective presence of DIS3 somatic mutations in haematological cancers is the prominent role exerted by MYC, and to a lesser extent by RAS, in these cancers." (PMID 25925570, 2015). "From the perspective of cancer progression, it can be speculated that DIS3 will enable cancer cells to regulate the expression of specific genes through means such as RNA degradation and other means." (PMID 34512342, 2021). "Therefore, the levels of DIS3 protein appear to be important and relevant to the progression of many commonly occurring cancers." (PMID 29802118, 2018). "It seems to be over-expressed in some cancers and under-expressed in others, whilst displaying loss-of-function mutations in AML, suggesting the role of DIS3 might differ within the context of different tissues and tumourigenic pressures." (PMID 26193331, 2015). "Silencing of DIS3 alone affects the viability, migration and invasion of cancer cells." (PMID 26517092, 2015). "We will discuss the structural and catalytic properties of DIS3, as well as its molecular and biological functions, role in disease and common genetic patterns observed in patients, in order to provide a basis on which to investigate the role of DIS3 in cancer progression." (PMID 26193331, 2015). "Nevertheless, we do not understand how DIS3 mutations can lead to cancer." (PMID 26193331, 2015). "An inspection of CRISPR screening of 1054 cancer cell lines using DepMap showed that EXOSC1–10 and DIS3 (EXOSC11) are essential in most cancer cell lines." (PMID 34948199, 2021). "DIS3 and DIS3L are known mainly for their roles in the RNA exosome complex, and several reports have shown that these molecules are closely involved in miRNA biogenesis and cancer recurrence." (PMID 38689093, 2024). "The precise role of DIS3 in cancer progression is not at all clear." (PMID 29802118, 2018).
cancer (continued). "We found that MHC-I scores were higher in cancer cells without expression of PIP5K1A, NCKAP1, CYFIP1, DIS3, TBP, and EXCO1." (PMID 39408874, 2024).
infection (2 papers, 2016 to 2024). The state of being infected such as from the introduction of a foreign agent such as serum, vaccine, antigenic substance or organism. "Pf. dis3 (upregulated by 6.28 ± 0.36 fold on day 3 post-infection) encodes a ribonuclease that is essential for mitotic control of the fission yeast Schizosaccharomyces pombe." (PMID 27911910, 2016). "Detection of Hsps, such as Hsp22 and Hsp100, were significantly increased at 72 h post-infection, and DIS3 was revealed to significantly increase at 48 h and 72 h in EVs post-infection." (PMID 39091390, 2024).
DIS3 also shares sentences with these, for which no sentence is quoted: Perlman syndrome (2 papers); adenoma (1); blood cancers (1); cystadenoma (1); dyscrasia (1); gastric cancer (1); malaria (1); Mendelian diseases (1); metastatic cancer (1); skin cancer (1).